LINC00968 (long independently transcribed non-coding RNA 968)
Gene: Long non-coding RNA gene on chromosome 8 (56,494,305 to 56,560,407, reverse strand). Ensembl gene ENSG00000246430.
Diseases named in the same sentence as LINC00968 in open-access papers:
LINC00968 is named in the same sentence as 17 diseases in open-access papers, as found by Europe PMC text mining. Sharing a sentence is not in itself a finding about the gene and the disease. The quoted sentences say what the papers report.
breast carcinoma (4 papers, 2017 to 2024). "Low LINC00968 expression has recently reported associated with poor prognosis in breast cancers by attenuating drug resistance." (PMID 31921296, 2019). "The consistent results were found in breast cancer (BRCA), LUAD and thymoma (THYM), revealing that LINC00968 level was significant lower in these cancers compared with para-noncancerous tissues." (PMID 28977863, 2017).
lung carcinoma (3 papers, 2020 to 2024). "In NSCLC, linc00968 serves as oncogene in lung cancer through activating the Wnt signaling axis." (PMID 33159015, 2020). "However, whether linc00968 could regulate the EMT of lung cancer by pairing with miRNAs is still largely unknown." (PMID 33159015, 2020).
gastric cancer (2 papers, 2021 to 2025). A primary or metastatic malignant neoplasm involving the stomach. "According to the survival data from the GEPIA database, higher expression of LINC00968 was significantly associated with the overall survival rate and disease-free survival rate of gastric cancer, indicating its significant prognostic value in gastric cancer." (PMID 40069867, 2025). "In conclusion, upregulated LINC00968 in gastric cancer served as a tumor promoter regulating cell growth and metastasis via modulating the miR-3202/VIRMA axis and regulating KIAA1429." (PMID 40069867, 2025). "LINC00968 contributes to the enhanced cell growth and metastasis of gastric cancer, which was mediated by KIAA1429-mediating m6A modification and the miR-3202/VIRMA axis." (PMID 40069867, 2025). "Animal modeling is also an effective way to deeply reveal the significance and function of LINC00968 in gastric cancer." (PMID 40069867, 2025). "Overexpressing KIAA1429 enhanced the expression of LINC00968 and mediated the effect of LINC00968 on gastric cancer cells in an m6A manner." (PMID 40069867, 2025). "LINC00968 is located on chromosome 12q 12.1 and its abnormal expression and potential significance in the occurrence and development of gastric cancer were primarily discovered in recent studies, which primarily observed the potential of LINC00968 in ferroptosis and prognosis of gastric cancer." (PMID 40069867, 2025). "Therefore, future studies would be devoted to constructing in vivo gastric cancer animal models to complete the role of LINC00968 in gastric cancer." (PMID 40069867, 2025). "Significantly increased LINC00968 was observed in gastric cancer cells." (PMID 40069867, 2025). "Whether LINC00968 could regulate the progression of gastric cancer remains unknown, which is critical for the identification of novel biomarkers." (PMID 40069867, 2025). "Overexpression of KIAA1429 significantly enhanced LINC00968 and could reverse the inhibitory effect of siRNA-LINC00968 in gastric cancer cells (P < 0.01)." (PMID 40069867, 2025). "Moreover, overexpressing KIAA1429 could also alleviate the suppressed cell proliferation (P < 0.01), migration (P < 0.01), and invasion (P < 0.01) of gastric cancer by LINC00968 knockdown." (PMID 40069867, 2025). "Therefore, m6A methylation mediated by KIAA1429 was speculated to be involved in the function of LINC00968 in gastric cancer." (PMID 40069867, 2025). "Therefore, LINC00968 was speculated to regulate the progression of gastric cancer cells via modulating the miR-3202/VIRMA axis and further regulating KIAA1429." (PMID 40069867, 2025). "Similarly, LINC00968 was also found to be upregulated in gastric cancer cells in the present study, and its knockdown dramatically suppressed cell growth and metastasis, suggesting its potential tumor promoter role in gastric cancer." (PMID 40069867, 2025). "This study aimed to evaluate the function of lncRNA LINC00968 in gastric cancer biological processes, and we discovered the role of KIAA1429, a typical m6A eraser, in mediating LINC00968 function." (PMID 40069867, 2025).
hepatocellular carcinoma (2 papers, 2020 to 2021). A malignant tumor that arises from hepatocytes. "For instance, METTL3-mediated m6A modification led to LINC00958 upregulation through stabilizing its RNA transcript, and LINC00968 sponged miR-3619-5p to upregulate HDGF expression thereby facilitating the lipogenesis and progression of hepatocellular carcinoma (HCC)." (PMID 32982586, 2020).
lung adenocarcinoma (2 papers, 2024 to 2025). A carcinoma that arises from the lung and is characterized by the presence of malignant glandular epithelial cells. "LINC00968 has also been suggested to mediate tumor progression of several human cancer, such as lung adenocarcinoma, osteosarcoma, and ovarian cancer." (PMID 40069867, 2025). "LINC00968 was downregulated in lung adenocarcinoma, which suppressed tumorigenesis and metastasis and inhibited cell growth." (PMID 40069867, 2025).
Age-related cataract (1 paper, 2021). A type of cataract (opacification of the lens) that forms during the course of aging. "Some of these genes associated with age-related cataracts include FRMD4B, NAALADL2, LOC105377670, LINC00968, LOC101929415, CTNNA3, LOC107984170, PRCP, and ZNF423, whereas others with a reduced risk include CFAP74, ACSL1, LOC101927668, LOC105369844." (PMID 34299682, 2021).
autoimmune disease (1 paper, 2025). A disorder resulting from loss of function or tissue destruction of an organ or multiple organs, arising from humoral or cellular immune responses of the individual to their own tissue constituents. "Thus, XFC exerts therapeutic effects via the ALKBH5/LINC00968/m6A pathway, providing a compelling example of TCM targeting epitranscriptomic mechanisms in autoimmune diseases." (PMID 41479914, 2025).
bladder cancer (1 paper, 2022). "Through an integrative analysis with bioinformatics methods, we identified a nine-lncRNA signature (including MIR497HG, LINC00968, NALCN-AS1, LINC02321, RNF144A-AS1, MNX1-AS1, FLJ22447, LINC01956, and FLJ42969) to predict the OS and prognosis of bladder cancer patients." (PMID 35693359, 2022).
Cryptococcal meningitis (1 paper, 2019). Meningeal inflammation produced by cryptococcus neoformans, an encapsulated yeast that tends to infect individuals with acquired immunodeficiency syndrome and other immunocompromised states. "The expression of the lncRNAs, ECRP, LINC00968, DPY19L1p1, DEFA8P, and DEFT1P2 was higher but the expression of the lncRNAs DDX11L10 and MTMR9LP was lower in cryptococcal meningitis patients than in healthy controls, which was consistent with the chip analysis results." (PMID 30767376, 2019).
diabetic nephropathy (1 paper, 2021). "Moreover, LINC00968, which is co-expressed with ENG and VCAM1, can promote the proliferation and migration of endothelial cells and accelerate the proliferation and fibrosis in diabetic nephropathy." (PMID 33790949, 2021).
epithelial ovarian cancer (1 paper, 2022). "However, LINC00968 promotes the progression of epithelial ovarian cancer regulating by ERK and AKT pathways." (PMID 35874989, 2022).
lymph node metastasis (1 paper, 2020). "The dysregulated expression of linc00968 was negatively related to the lymph node metastasis (LNM) and clinical stage." (PMID 33159015, 2020).
tumor (13 papers, 2019 to 2025). "Overexpression of LINC00968 inhibited BC cell proliferation, migration, and tube formation in vitro as well as tumor growth in vivo through inhibition of miR-423-5p, which downregulated PROX1." (PMID 37175800, 2023). "Recent experimental results manifested that the inhibition of LINC00968 can significantly decrease the proliferation of tumor cell and could be regard as an oncogene in various cancers." (PMID 38475660, 2024). "LINC00968 serves as oncogenic or tumor-suppressive roles in different cancer types." (PMID 35874989, 2022). "Low levels of LINC00968 expression are associated with poor clinical outcomes, as LINC00968 has decreased expression in the advanced tumor TNM stage, tumor cell differentiation, neoplasm recurrence, and poor patient survival." (PMID 33147570, 2020). "LINC00968 has been studied mainly in cancer pathogenesis; it may promote tumor cell growth, migration, and invasion upon activation of Wnt/β-catenin or by targeting cyclin-A2." (PMID 31547203, 2019). "Tumour stage significantly associated with the expression of LINC00673 (p = 0.005), LINC01929 (p = 0.002), PCAT19 (p = 0.001), FENDRR (p = 8.33 × 10–6), SVIL-AS1 (p = 0.037), LANCL1-AS1 (p = 8.69 × 10–7), LINC00968 (p = 2.32 × 10–7) and ADAMTS9-AS2 (8.29 × 10–6) as determined by Kruskal–Wallis test." (PMID 32020063, 2020). "The co-regulation of LINC00857, LINC00968, LINC00663, and ITGA9-AS1 on SOX2 suggested their potential contributions in aberrant sialylation process during tumor progression." (PMID 38632255, 2024). "LINC00968 is significantly downregulated in LUAD and inhibits tumor proliferation, migration and invasion, and may serve as a prognostic marker and potential therapeutic target for LUAD." (PMID 36171881, 2022). "We showed that C14orf132 and LINC00968 were downregulated in tumors (NSCLC, LUAD and LUSC) in comparison to matched normal lung tissue and not statistically significant in LUAD tumor vs. LUSC tumor." (PMID 35053601, 2022).
cancer (11 papers, 2017 to 2025). A tumor composed of atypical neoplastic, often pleomorphic cells that invade other tissues. "In addition, LINC00968 was found to be closely associated with ferroptosis and N-6 methylation (m6A), and could attenuate drug resistance in cancer cells." (PMID 36171881, 2022). "Recently, increasing studies elucidate that aberrantly expressed linc00968 play vital roles in the tumorigenesis of cancers through involving to diverse biological behaviors." (PMID 33159015, 2020). "Meanwhile, LINC00968 also plays critical role in the development of various cancers." (PMID 40069867, 2025). "LINC00968 is heterogeneous and plays different roles in various cancers." (PMID 39132150, 2024). "The levels of linc00968 in LUAD and para-carcinoma tissues from 56 cases of patients with LUAD were detected using qRT-PCR." (PMID 33159015, 2020).
infection (1 paper, 2019). The state of being infected such as from the introduction of a foreign agent such as serum, vaccine, antigenic substance or organism. "Thus, expression of LINC00968, LINC01105, lnc-SGK1, MHRT, MIR17HG, and NeST were only or largely impacted in GPHT infection." (PMID 31547203, 2019).
LINC00968 also shares sentences with these, for which no sentence is quoted: osteosarcoma (3 papers); thymoma (1).